HMGA2 (high mobility group AT-hook 2)
Diseases named in the same sentence as HMGA2 in open-access papers (continued):
Sharing a sentence is not in itself a finding about the gene and the disease.
cancer (continued). "Numerous studies have reported that aberrant overexpression of HMGA2 is associated with increased invasion, stemness and poor prognosis in cancer." (PMID 29245994, 2017). "High-level expression of Hmga2 in mesenchymal and epithelial cancer cells has been linked to rearrangements and mutations of HMGA caused by chromosomal translocations involving the HMG locus." (PMID 28415789, 2017). "High cellular HMGA2 levels are linked to increased malignancy, enhanced metastatic potential, and poor clinical outcome in different cancer types." (PMID 28500786, 2017). "This dual telomere- and HMGA2-targeted treatment caused severe telomere dysfunction and genomic instability in cancer cells." (PMID 26799419, 2016). "Having shown that HMGA2 diminishes telomere-mediated genomic instability in human cancer cells, we wanted to determine if the loss of this telomere protective role of HMGA2 involves changes in 3D telomere architecture." (PMID 26799419, 2016). "We had shown previously that loss of HMGA2 promotes increased genomic instability and this coincided with the occurrence of dicentric chromosomes in cancer cells, which are the result of impaired telomere end protection." (PMID 26799419, 2016). "A strong decrease of let-7 expression levels has been associated with an aberrant overexpression of HMGA1 and HMGA2 in several human highly malignant carcinomas." (PMID 25859543, 2015). "The Hmga2 mRNA is degraded by let-7 miRNA in several cancer cell lines, and the loss of let-7 induces the expression of Hmga2." (PMID 24747725, 2014). "HMGA2 over expression in itself is a hallmark for both benign and malignant tumors and also linked to a highly malignant phenotype with a poor prognostic index." (PMID 25546138, 2014). "Further, multivariate risk factor analysis demonstrated that HMGA2 expression was found to be a significant independent predictor of death of carcinoma and as an independent prognostic marker for disease-specific overall survival." (PMID 25245141, 2014). "Increased tumorigenicity and invasion with increased LIN28A expression can be explained mechanistically by down-regulation of let-7 microRNAs and up-regulation of let-7 targets such as HMGA2, a chromatin modifying gene that is associated with numerous cancers." (PMID 23846349, 2013). "Among the PRCa genes expressed at the protein level are transcriptional regulators (Hdac2 and Hmga2), cancer-linked genes (Klf4 and Kit), and genes involved in glycolysis and pyruvate metabolism (Hk1, Eno2, and Pck2)." (PMID 22305566, 2012). "HMGA2 is an architectonic transcription factor abundantly expressed during embryonic and fetal development and it is associated with the progression of malignant tumors." (PMID 21533145, 2011). "High mobility AT-hook 2 (HMGA2) is a chromatin-associated protein implicated in the development and progression of benign and malignant tumors as well as stem cell self-renewal." (PMID 21533145, 2011). "HMGA2 expression has been shown to be associated with enhanced selective chemosensitivity towards the topoisomerase (topo) II inhibitor, doxorubicin, in cancer cells." (PMID 17222355, 2007). "HMGA2 is often associated with cancer progression and metastasis." (PMID 40394416, 2025). "Previous studies have shown that HMGA2 mRNA is a target of several microRNAs, thereby polymorphisms located in the 3’ UTR of the HMGA2 gene can lead to alterations of miRNA binding sites that may be linked to cancer risk." (PMID 38802807, 2024). "Studies also indicate a strong association between the HMGA2 gene and cancer." (PMID 38473181, 2024). "On the other hand, the association of HMGA2 with cisplatin sensitivity has been controversial in different tumors; while in some cancers, HMGA2 levels have been related with cisplatin sensitivity, in other tumors, it has been associated with resistance to this drug." (PMID 36614297, 2023).
cancer (continued). "Overexpression of HMGA2 in malignant tumors has been associated with a poorer prognosis and may be associated with cancer cells showing stem cell-like behaviors." (PMID 35617214, 2022). "However, in tumors of mesenchymal and epithelial origin, high levels of HMGA2 protein expression are observed and are associated with poorer OS in multiple types of cancer." (PMID 36568239, 2022). "Expression of HMGA2 enhances metastasis and is associated with poor prognosis of cancers." (PMID 33568150, 2021). "In addition, gene set enrichment analysis (GSEA) showed that HMGA2 expression was associated with the expression of genes of the NF-kB and general cancer pathways." (PMID 34680349, 2021). "Furthermore, suppression of HMGA2 in vitro significantly inhibits cancer cell mobility and the expression of EMT hallmark proteins." (PMID 33668453, 2021). "In this review, we discuss these oncogenic roles of HMGA2 in different types of cancers and propose that HMGA2 may be used for cancer diagnostic, prognostic, and therapeutic purposes." (PMID 33668453, 2021). "In addition, the impact on the survival of cancer patients was most significant for overexpression of HMGA2, a collagen-encoding gene and MMP9." (PMID 32577156, 2020). "HMGA2 is associated with human malignant tumors and neoplastic transformation of thyroid cells." (PMID 32752229, 2020). "Besides, HMGA2 overexpression is linked to initial of metastasis and poorly prognostic status in a large number of cancers types." (PMID 32952599, 2020). "High HMGA2 expression in cancers is commonly associated with under-expression of let-7." (PMID 32979259, 2020). "Expression of HMGA2 in cancer is associated with poor prognosis for patients." (PMID 30289618, 2019). "HMGA2 expression is associated with cellular transformation, directly correlates with the level of malignancy, and is linked to enhanced metastatic potential and poor clinical outcome in different cancers." (PMID 30289618, 2019). "Here, by employing our four previously established cancer cell models, we first investigated whether HMGA2 affects DNA damage caused by the clinically relevant TOP2 poison Etop." (PMID 31271486, 2019). "Significant association between HMGA2 overexpression and poor OS was found in 14 types of cancers." (PMID 29997523, 2018). "Cancer cells from KPHetCT;Hmga2+/+ and KPHetCT;Hmga2CK/CK mice express Hmga1 at similar levels, therefore Hmga1 could compensate for Hmga2 deficiency to enable malignant transformation and metastasis." (PMID 30228296, 2018). "Recently, evidence has implicated HMGA2 having complex functions in cancer." (PMID 29416690, 2018). "Overexpression of the HMGA2 gene is linked to the development of cancer." (PMID 26858029, 2016). "HMGA2 overexpression, dysregulation, or truncation has been linked to benign and malignant tumors." (PMID 24723911, 2014). "The function of HMGA2 as an oncoprotein may be associated with several important molecules involved in invasion and metastasis of cancer cells." (PMID 23599793, 2013). "In addition, high mobility group A2 (HMGA2), an oncogene frequently mutated in multiple types of cancers, is also hindered by let-7." (PMID 23075324, 2012). "Thus, the elucidation of molecular mechanisms that underlie the effects of HMGA2 on cancer invasion and patient survival by mediating EMT may offer new therapeutic methods for preventing cancer progression." (PMID 38361784, 2024). "In addition, the regulatory association of SMYD3 with HMGA2 could be generalized to a pan-cancer level." (PMID 37237385, 2023). "Our meta-analysis showed that HMGA2 likely played an important role in human cancers and overexpression of HMGA2 could be associated with aggressive biological behavior although its prognostic values varied in different types of cancers." (PMID 29997523, 2018).
cancer (continued). "We found several let-7 microRNAs to be differentially expressed comparing high and low HMGA2 gene expression; let-7a, let-7c and let-7f was seen inversely correlated, consistent with the biological presumption that loss of let-7 inhibition leads to HMGA2 overexpression in cancer." (PMID 26858029, 2016). "HMGA2 rs1042725 has been reported to contribute to height variability in European population, and US Caucasian and Chinese populations, but not in Korean and Japanese population To our knowledge, this is the first study that reports the association between rs1042725 in HMGA2 gene and cancer." (PMID 27677077, 2016). "The C1 cluster highly expressed HMGA2, which was upstream mediator of cancer hallmarks and targets many critical signalling pathways." (PMID 41469334, 2026). "Studies using immunohistochemistry (IHC) to evaluate HMGA2 in cancer have suggested considerable clinical utility of HMGA2 analysis." (PMID 40518465, 2025). "In line with our data, the TCGA dataset identified only a small set of HMGA2 positive cancers with a markedly adverse prognosis in ccRCC while the group of positive cancers was much larger in papillary RCC, where the prognostic impact was less stringent." (PMID 40518465, 2025). "During cancer progression, the regulatory mechanisms controlling HMGA2 gene expression are often disrupted." (PMID 40853523, 2025). "HMGA2 is overexpressed in various types of cancer, such as lung cancer, gastric cancer, and breast cancer." (PMID 39885614, 2025). "In recent years, Hmga2 has emerged as a key focus in diverse fields such as cancer biology, developmental biology, and gene regulation." (PMID 40884260, 2025). "A study conducted with a large sample demonstrated that HMGA2 can effectively differentiate between benign and malignant tumors among follicular neoplasms, with a sensitivity of 72%." (PMID 40346322, 2025). "We also found a correlation between plasma HMGA2 level and BC grade, which is essentially related to the differentiation status of cancer cells; the higher the grade is, the less common the differentiation and the poorer the prognosis." (PMID 40204943, 2025). "Data from the “The Cancer Genome Atlas” TCGA database also show a striking prognostic role of high HMGA2 expression." (PMID 40518465, 2025). "Despite its documented roles in other cancers, HMGA2’s prognostic and immunomodulatory functions in EC remain poorly defined." (PMID 40703517, 2025). "In adulthood, HMGA2 expression decreases but is re-expressed in diseases, including cancer and diabetes, where its effects are context-dependent." (PMID 40141058, 2025). "HMGA2 also induces transforming growth factor beta 2 (TGFβ-2) receptor expression, activates the TGFβ signaling pathway, and facilitates cancer cell metastasis." (PMID 40475780, 2025). "Nuclear HMGA2 expression was generally markedly higher in cancer than in corresponding normal tissues." (PMID 40518465, 2025). "The involvement of let-7 is consistent with previous computational and experimental analyses implicating let-7 in the regulation of HMGA2 expression in other cancer-derived cell lines." (PMID 40867050, 2025). "This study investigates MDM2 amplification in HMGA2-altered pleomorphic adenoma, atypical pleomorphic adenoma, and carcinoma ex pleomorphic adenoma." (PMID 40338436, 2025). "In this multicenter, retrospective case series analysis, we examined 37 cases of HMGA2-altered pleomorphic adenoma, carcinoma ex pleomorphic adenoma, and pleomorphic adenoma with atypical features." (PMID 40338436, 2025). "Most previous studies demonstrated that HMGA2 plays a key role in cancer growth, invasion, and the EMT phenotype, which involved the interactions of multiple signaling proteins and non-coding RNAs." (PMID 38361784, 2024). "Although barely detectable in differentiated tissues, HMGA2 is highly expressed in embryonic tissues and malignant tumors." (PMID 38361751, 2024).
cancer (continued). "Massive miRNAs have been clarified to affect EMT and invasion of cancers through regulating the expression of HMGA2." (PMID 38361784, 2024). "Among them, the expressions of Cdkn1a, Hmga2, Thbs1 and Cdkn2a in MicroRNAs that promote cell differentiation in cancer pathways increased, indicating that the differentiation of SSCs is dominant." (PMID 38397131, 2024). "HMGA2 is relatively abundant in the early embryo and most types of cancer; however, it exhibits lower expression in adult tissues." (PMID 38361784, 2024). "Analysis of surgical specimens of GC and clinical pathological data from patients with cancer showed that HMGA2 overexpression was compared with normal epithelium." (PMID 38361784, 2024). "In age-related cancers such as lung cancer, breast cancer, colorectal cancer, and prostate cancer, elevated expression of HMGA1 and HMGA2 is correlated with increased self-renewal, invasiveness, and drug resistance in cancer cells." (PMID 39507236, 2024). "It was found that lncRNAs significantly affect the EMT of cancers by modulating the miRNA/HMGA2 axis." (PMID 38361784, 2024). "It was reported that high expression of HMGA2 in cancer changes the cell phenotype from epithelial to mesenchymal." (PMID 38361784, 2024). "High expression of HMGA2 was associated with EMT and metastasis and predicted poor prognosis in patients with cancer." (PMID 38361784, 2024). "Clinically, 3% of patients showed changes in HMGA2, which were more common in cancers that had metastasized to bones, lymph nodes, and the liver." (PMID 39123360, 2024). "The development of targeted therapies against HMGA2 holds promise for reducing cancer incidence and improving prognosis across various cancer types." (PMID 39085703, 2024). "Although the higher expression of HMGA2 was observed in cancer than adjacent tissue, more samples would be necessary to solid the results." (PMID 38845972, 2024). "The HMGA2 protein is overexpressed in various cancers, such as pancreatic cancer and lung cancer, and is associated with a poor prognosis." (PMID 39123360, 2024). "Apart from lncRNAs, circRNAs (as upstream regulatory targets) affect EMT in cancers by modulating the miRNA/HMGA2 axis." (PMID 38361784, 2024). "Proteins, such as HMGA1a, HMGA1b, and HMGA2, frequently overexpressed in cancers, like thyroid, colorectal, and ovarian carcinomas, are modulated by miRNAs and play roles in tumorigenesis." (PMID 39684593, 2024). "Overexpression of circ_0000267 in GC tissues and cell lines is related to cancer progression through regulation of the miR-503-5p/HMGA2 axis." (PMID 38361784, 2024). "We also demonstrated that HMGA2 mitigated the sensitivity of cancer cells to combination treatment with a ferroptosis inducer and mTORC1 inhibition or gemcitabine." (PMID 38493165, 2024). "Lin-7 also targets the high mobility group AT-Hook 2 (HMGA2), a transcriptional factor functioning as an oncogene, especially in less differentiated cancers." (PMID 38899393, 2024). "GO, KEGG, Reactome and Wikipathway analyses using Enrichr have revealed that HMGA2 play a role in the process including cellular senescence, DNA repair, differentiation and chromatin remodeling and importantly in miRNA and cancers." (PMID 38802807, 2024). "In cancer treatment, HMGA2 can assist cancer cells in repairing DNA damage and overcoming cell cycle repression induced by drugs." (PMID 38493165, 2024). "HMGA2 is either lowly expressed or not expressed in adult tissues, whereas it is highly expressed in malignant or cancer cells, implying the oncogenic role of HMGA2." (PMID 38845972, 2024).
cancer (continued). "HMGA2, which is actively involved in epithelial-mesenchymal transition, migration, and invasion of cancer cells, was also markedly reduced in LNCaP cells as compared to DU145." (PMID 39741355, 2024). "The high-mobility group AT-hook 2(HMGA2) gene has been widely studied in the context of cancer and animal growth." (PMID 38473181, 2024). "Increasing evidence indicates that HMGA2 is an independent prognostic marker for malignant tumors and that the expression level of HMGA2 is related to the efficacy of certain chemotherapeutic drugs." (PMID 39591457, 2024). "A study demonstrated that the Lin-28B/let-7/HMGA2 axis was activated by STAT3/nuclear factor kappa B (STAT3/NFKB) to regulate the EMT/cancer stem cell formation; of note, HMGA2 plays a major role in this axis." (PMID 38361784, 2024). "Silencing of HMGA2 resulted in reduction of oxidative stress in HBx-expressing cells, and correspondingly, this cancer growth promotion effect is diminished together with the suppression of HMGA2 expression." (PMID 38464387, 2024). "HMGA2 protein plays a crucial role in maintaining the undifferentiated state of cancer cells and their self-renewal properties." (PMID 39085703, 2024). "RNA sequencing comparisons between cancerous and normal tissues have revealed diverse expression patterns of HMGA2 across various cancer types." (PMID 38473181, 2024). "Previous research reported the significant role of HMGA2 in the metastasis of cancer via the regulation of EMT mediated through transcription factors including Slug, SNAI1, as well as Twist20." (PMID 38671227, 2024). "Typically, HMGA2 shows greater expression in sarcomas, brain and central nervous system tumors, as well as in cancers of the esophagus, head and neck, lung, melanoma, ovary, and pancreas, relative to their normal tissue counterparts." (PMID 38473181, 2024). "With ongoing research, HMGA2 has been recognized as being extensively involved in the development and progression of various malignant tumors." (PMID 39591457, 2024). "Compared to embryonic tissues, normal adult tissues express HMGA2 at a lower level, whereas HMGA2 is frequently up-regulated in cancers and transformed cells." (PMID 38836981, 2024). "Paradoxically, HMGA2 can also play a pro-apoptotic role as a defense mechanism to eliminate cancer cells harboring fatal genetic defects." (PMID 39085703, 2024). "Conversely, tumor-suppressor miRNAs, such as let-7, which targets oncogenes like RAS, MYC, and HMGA2, are frequently downregulated in cancer." (PMID 39684593, 2024). "Both proteins were highly expressed in cancer tissue, with αSMA signals in the connective tissue and HMGA2 located within cancer cells." (PMID 38493165, 2024). "HMGA2 is expressed in embryonic tissues and is frequently upregulated in aggressively growing cancers, including CRC." (PMID 36980621, 2023). "For instance, the practical application value of HMGA2 in early cancer diagnosis and prognostic assessment requires further validation." (PMID 38304037, 2023). "High Mobility Group AT-Hook 2 (HMGA2) has been found to be involved in the maintenance of cancer stem cell properties and regulates HNSCC/OSCC development and progression." (PMID 37237385, 2023). "This review will focus on the known molecular mechanisms by which HMGA2 exerts genome protective functions that contribute to cancer cell survival and chemoresistance in CRC." (PMID 36980621, 2023). "Overall, HMGA2 acted as a cancer promoter to facilitate the proliferation, migration, and invasion of GC cells." (PMID 37529164, 2023). "In a cancer context, increased HMGA2 expression in CRC corresponds with enhanced cellular growth, differentiation, proliferation, transformation, angiogenesis, epithelial-to-mesenchymal transition, apoptosis and metastasis." (PMID 36980621, 2023). "Many studies have reported that c-Myc targets the promoters of HMGA1 and HMGA2, transcriptionally enhancing their expression in various types of cancer, including PDAC." (PMID 37370109, 2023).